MTOR (mechanistic target of rapamycin kinase)
Diseases named in the same sentence as MTOR in open-access papers (continued):
Sharing a sentence is not in itself a finding about the gene and the disease.
tumor (continued). "Western blot analysis of the xenograft tumours revealed that the combination of biochanin A and SB590885 inhibited activation of the ERK MAPK and PI3K/AKT/mTOR signalling pathways in the in vivo xenograft model." (PMID 32774165, 2020). "Imperatorin show anti-tumor properties by inhibiting the phosphorylation of PI3K, Akt, and mTOR in human gastric adenocarcinoma cells." (PMID 33344242, 2020). "For example, lncRNA-PAGBC competitively binds to the tumor suppressive microRNAs miR-133b and miR-511 and therefore titrates miRNAs off their binding sites on SOX4 and PIK3R3, which then activates AKT/mTOR pathway in gallbladder cancer." (PMID 32123162, 2020). "Another molecular mechanism related to tumor adaptation and resistance against 5-ALA-PDT photo-oxidation relies on the anti-necrotic role of NFκB via the increase in AKT/mTOR signaling, at least for glioblastoma U87 and LN18 cells." (PMID 33552982, 2020). "IGF-1R binding with either IGF-1 or IGF-2 will undergo receptor autophosphorylation and cross-linking, and then the signals activate both PI3K/Akt/mTOR and Ras/Raf/MEK/ERK pathways to enhance tumor progression." (PMID 32498447, 2020). "Triple-negative tumours with overexpression of EGFR exhibit constitutive activation of EGFR-dependent signalling pathways, especially the PI3K/AKT/mTOR pathway." (PMID 32286420, 2020). "There are a variety of autophagy-related signaling pathways available in tumor cells, with the PI3K/AKT pathway as a classical activator of mTOR to induce autophagy." (PMID 31911756, 2020). "Expression levels of many proteins were altered with resistance development including gp100/PMEL, CD171/L1CAM, GAB2, mTOR and PI3K-p85 which have been previously shown to be upregulated in tumors including CMM and promoting tumor progression." (PMID 33082316, 2020). "mTOR signaling and CXCL12/CXCR4 axis have been reared as a positive feedback loop to influence the tumor migration and CXCL12 secretion." (PMID 32483450, 2020). "In our study, we show that Apigenin can effectively inhibit the activation of PI3K and proteins like p-mTOR, p-AKT, p-IKK, p-p65 involved in PI3K signal pathway, thereby effectively achieve the anti-tumor effects." (PMID 32127939, 2020). "Combination treatment with an IGF-1R inhibitor and CDK4/6 inhibitor demonstrated synergistic activity by inhibiting tumor growth and survival of ES cells in vivo and in vitro through the suppression of PKC/AKT/mTOR and activation of RB." (PMID 32754598, 2020). "Of these, copanlisib exerts the most potent antitumor effects, markedly inhibiting cell proliferation, survival, and tumor growth by suppressing PI3K/mTOR/Akt activities in mouse models generated from MCC cell xenografts and patient-derived tumor xenografts." (PMID 32483262, 2020). "It revealed that CDX-LIPO can suppress GBM growth by targeting mTOR pathway, inducing autophagy and ICD, and regulating tumor metabolism and TIME." (PMID 32817393, 2020). "In the current study, we confirmed that DMC-BH significantly decreased the expression of p-Akt and p-mTOR compared with DMC and control in orthotopic tumor tissues." (PMID 33221748, 2020). "Our findings demonstrated comparable and consistent results, which indicated that GAL1-mediated tumor invasion and metastasis occurs through the FAK/PI3K/AKT/mTOR pathway." (PMID 32225123, 2020). "In conclusion, FGF14 is a novel tumor suppressor, which suppresses cell proliferation and induces cell apoptosis via mediating PI3K/AKT/mTOR pathway." (PMID 31949485, 2020). "When combined with mTOR inhibitor rapamycin, SMURF1 silencing resulted in the increased tumor sensitivity to rapamycin leading to significant inhibition of tumor growth in an orthotopic GB model." (PMID 32984016, 2020). "Taken together, these results suggest that downregulation of PHLDA2 inhibits tumor growth and PI3K, thereby promoting autophagy and inhibiting EMT, in part through the PI3K/AKT/mTOR and PI3K/AKT/GSK-3β signaling pathways." (PMID 32385195, 2020).
tumor (continued). "All different assay techniques suggested sensitivity of the patient’s tumor cells towards inhibition of MAPK signaling pathway targets MEK and mTOR." (PMID 32576176, 2020). "Thus, BHLHE40-mediated tumor suppression can be traced to inhibition of oncogenic factors such as STAT1, whereas BHLHE40-mediated promotion of tumor progression may be traced to the activation of the PI3K/Akt/mTOR pathway and the upregulation of pro-survival factors such as survivin and clusterin." (PMID 32577154, 2020). "In tumor cells, EZH2 epigenetically represses negative regulators of mTOR (e.g., TSC2 and RHOA), thus inhibiting tumor cell autophagy and accelerating tumorigenesis." (PMID 32999031, 2020). "Since WGS suggested PI3K/AKT/mTOR and Ras/Raf/MEK/ERK activation were key mechanisms driving the growth of this tumour, we further explored the RNAseq data to validate these findings." (PMID 33053751, 2020). "The current study tested the potential anti-tumor activity of VS-5584, a novel dual inhibitor of PI3K/mTOR, in RCC cells." (PMID 33051401, 2020). "In the last years, preclinical and clinical research focused on targeting different pathways involved in tumor growth, such as PI3K/Akt/mTOR, cyclinD/CDK/pRb pathways and tumor microenvironment." (PMID 33105796, 2020). "In vivo, DHA inhibited the tumor growth of ESCC patient-derived xenografts and weakened p-mTOR, p-p70S6K, and p-RPS6 expression in tumor tissues." (PMID 33658929, 2020). "As a result, defects of the translation machinery alter the expression of tumor-promoting proteins like KRAS, mTOR and MYC which, in turn, directly affect transcription of several important RNAs and drive carcinogenesis." (PMID 33092114, 2020). "In renal carcinoma, kruppel-like factor 6 (KLF6) activates mTOR signaling and its downstream lipid metabolism regulator, SREBP-2 to enhance tumor growth." (PMID 32974183, 2020). "Together, mTOR signaling promotes the PEG-mediated CCL2 expression in both tumor cells and macrophages, thereby regulating macrophages chemotaxis to the tumor and acts as a potential target for anti-tumor immunotherapy." (PMID 32483450, 2020). "Differences in mTOR and LC3 transcripts emerged in tumor-free tissues, therefore particular attention should be considered in selecting the control group." (PMID 33362215, 2020). "Lately, using gene expression analysis, it was revealed that the activation of the PI3K/AKT/mTOR pathway and the inactivation of the PTEN tumor suppressor were the major alterations in MCF7 cell-derived BCSCs-enriched cells, compared to non-enriched cells." (PMID 33584277, 2020). "In summary, our data show that apatinib exerted antitumor effects in PTC by suppressing tumor growth, promoting apoptosis, and inhibiting migration through the PI3K/Akt/mTOR signaling pathway." (PMID 32219060, 2020). "Western blot analysis of tumor tissues showed that the levels of PI3K, p-Akt, and mTOR in CIPp tumors were reduced with disulfiram treatment, which was associated with the up-regulation of cleaved caspase-3 (p < 0.05)." (PMID 33375426, 2020). "This combination was able to further reduce tumor growth and resulted in almost stable disease, but the combination was not well-tolerated as has been described for MEK inhibitors and mTOR inhibitors in an adult clinical trial and had to be discontinued." (PMID 33353026, 2020). "Silencing of VDUP1 in NF1 tumours completely abolished cell death in response to mTOR and HDAC inhibitors, demonstrating that it was required in the induction of cell death following mTOR and HDAC inhibitors treatment." (PMID 33066259, 2020). "Further mechanistic analyses revealed that knockout of SNHG3 activated the AKT/mTOR/ERK pathway in PTC cell lines and the mTOR inhibitor AZD8055 abrogated the tumor-promoting effect induced by SNHG3 inhibition." (PMID 32284745, 2020). "It is reported that FBXW7 targets mTOR for degradation and cooperates with PTEN in tumor suppression." (PMID 32429412, 2020).
tumor (continued). "In a tumor cell, PI3K/AKT/mTOR is one of the main signaling pathways in the regulation of proliferation, invasion, and migration." (PMID 33142817, 2020). "In vitro experiments confirmed that adiponectin hampered tumour growth through the activation of AMP-activated protein kinase (AMPK) and subsequent suppression of mammalian target of rapamycin (mTOR) pathways." (PMID 33008076, 2020). "Combined with the effect of mTOR–pS2448 on the OS of HCC patients, we found that autophagy affects malignant tumor progression and is closely related to PI3K–AKT–mTOR signaling." (PMID 31988807, 2020). "FAM83A is involved in regulating a variety of different tumor-related signaling pathways, including the EGFR, RAS/RAF/MEK/ERK, and PI3K/AKT/mTOR pathways." (PMID 32195172, 2020). "While CUL7 also exerts a tumor-suppressive effect, as partially proven by the degradation of IRS-1, which is negatively mediated via the mTOR pathway." (PMID 33130829, 2020). "In vivo experiments showed that silencing FAM83A in A549 cells reduced subcutaneous tumor growth and lung metastasis as well as phosphorylation of ERK and PI3K/AKT/mTOR." (PMID 33344485, 2020). "Pro-EGCG such as octaacetate or peracetate-protected EGCG suppressed xenograft tumor growth, inhibited tumor angiogenesis, and reduced the expression of vascular endothelial growth factor A (VEGFA) and HIF1α by the PI3K/AKT/mTOR signaling pathway." (PMID 33113766, 2020). "The AKT/mammalian target of rapamycin (mTOR)/phosphoinositide-3 kinase(PI3K) signaling pathway plays a pivotal role in the development, survival, andproliferation of tumor cells, making it an attractive drug target." (PMID 33083527, 2020). "In addition, mTOR can regulate telomerase activity in hepatocarcinogenesis or may indirectly induce tumorigenesis by the suppression of autophagy, which plays a crucial role in tumor suppression by eliminating damaged cells." (PMID 33362215, 2020). "Next, we used the TCGA dataset to assess the impact of this mTOR signature on TAM‐MG phenotype and on the immune composition of the tumours." (PMID 32567735, 2020). "The activation of mTOR, an important downstream target of AKT, can promote angiogenesis by increasing VEGF expression or inducing HIF-1α-dependent gene expression in tumor cells." (PMID 33116125, 2020). "Upregulation of mTOR and fibroblast growth factor receptor 3 (FGFR3) inhibits tumour growth activated by tyrosine-protein kinase cellular sarcoma (c-SRC)." (PMID 33023154, 2020). "In a recently reported study, reduced mTOR activity resulted in reduced cell proliferation in HepG2 and Hep3B HCC cell lines and reduced tumor growth in xenograft mouse models." (PMID 32093152, 2020). "As an important tumor suppressor gene, PTEN negatively regulates PI3K/AKT/mTOR pathway, inhibiting cell growth and proliferation 37,38." (PMID 32913452, 2020). "Several studies have showed that Prdx1 promotes tumor occurrence mainly by adjusting the levels of ROS, TGF-β1, mTOR/p70S6K, and ROS/ERK/cyclin D1." (PMID 32357862, 2020). "The binding of ligand ignition in tumor cell function comprises antiapoptosis, proliferation and invasion through triggers of PI3K/Akt/mTOR, JAK/STAT and MAPK pathways activation." (PMID 33680380, 2020). "Oxygen deprivation was observed to promote LC3 processing and autophagosome formation in tumor cells, which are mediated by AMPK activation and by downregulation of mTOR." (PMID 31547619, 2019). "A reduction in protein levels of p-PI3K, p-AKT, p-mTOR, and p-P70S6K was detected in cardamonin-treated tumor tissues." (PMID 31455352, 2019). "For example, the tumour suppressor, phosphate and tensin homolog deleted from chromosome ten (PTEN), regulates the PI3K/AKT pathway which converges on mTOR." (PMID 35582282, 2019). "Combining IRES and mTOR therapies significantly decreases GBM cell proliferation in vitro, reduces tumor size in vivo, and increases overall survival in mice grafted with GBM cells." (PMID 31795417, 2019).
tumor (continued). "β-elemene significantly suppressed the insulin-driven cell growth and the activation of mTOR and PI3K in tumor cells, while the toxicity to normal hepatocytes was much lower." (PMID 30422809, 2019). "Beyond the demonstration of strong potential for driving tumor development in the preclinical setting, PIK3CA p.H1047R has shown sensitivity to the mTOR inhibitor everolimus." (PMID 31197119, 2019). "Tumor‐bearing nude mice assay results showed that LOC101928316 overexpression can significantly inhibit the p‐AKT3 and p‐mTOR protein expression levels in bearing nude tumor tissues." (PMID 31207155, 2019). "Another dual PI3K/mTOR inhibitor voxtalisib (SAR245409, XL765), a pyridopyrimidinone derivative, significantly inhibits tumor growth in multiple human xenograft models." (PMID 31277692, 2019). "The downregulation of phospho-AKT/phospho-mTOR after Salmonella treatment in both B16F10 and LL2 cells resulted in a decrease of MMP-9 expression which was reversed in tumor cells transfected with constitutively active AKT." (PMID 31052558, 2019). "In conclusion, the mTOR pathway is upregulated in a subset of patients with HCC undergoing LT, particularly within the tumour edge where cellular growth and proliferation are more intense." (PMID 30650598, 2019). "Conversely, inactivation of phosphatase and tensin homologue (PTEN), a potent tumour suppressor and negative regulator of PI3K, also leads to hyperactivation of PI3K-driven mTOR signalling." (PMID 30970654, 2019). "To determine whether the tumour-suppressive effects of SLC41A1 were associated with its function as an Mg2+ transporter, we evaluated the activity of Akt/mTOR in SLC41A1-overexpressing PDAC cells and found that the overexpression of SLC41A1 significantly inhibited Akt/mTOR activity." (PMID 31076559, 2019). "In conclusion, our study in vitro demonstrated that mTOR inhibition can extend the life span and enhance the antigen presenting and processing abilities of BMM-derived DCs even in the presence of tumor cells." (PMID 31052575, 2019). "A recent report showed that the depletion of PARK2 enhanced the activation of PI3K/AKT/mTOR and played an important role in maintaining the activation of PENT, which was a well-known tumor suppressor that inhibits the PI3K/AKT pathway." (PMID 31508359, 2019). "It has been reported that mTOR acts as downstream molecule of AKT1, and the AKT/mTOR pathway is one of the classic signalling pathways to mediate tumour metabolic homeostasis, which is beneficial for tumour growth and metastasis." (PMID 30717751, 2019). "Consistent with previous findings, our study confirmed that PARK2 exerted a tumor suppressive effect by regulating the activation of EGFR in NSCLC and inhibiting p-EGFR, p-AKT, and p-mTOR." (PMID 31508359, 2019). "We assessed the impact of CSCs in resistance to PI3K/mTOR pathway inhibition using LMS cell lines, a xenograft mouse model, and human tumor samples." (PMID 30683135, 2019). "In vivo study, the weight of tumour tissues at deoxyshikonin groups was significantly reduced compared with the control group, and PI3K, p-PI3K, Akt, p-Akt308 and mTOR expression was decreased." (PMID 31230505, 2019). "The reduced PML levels lead to a derepression of mammalian target of rapamycin (mTOR), which in turn participates in a feedback mechanism to amplify HIF-1α signaling, thus facilitating tumor progression." (PMID 31208103, 2019).
tumor (continued). "Despite having a tumour, the WL group had an increase in RAG-A 1.9-times when compared to W group (P = 0.004), which likely indicated that the stimulus that acted on the mTOR complex mostly resulted from the activation of RAG-A GTPases." (PMID 30975087, 2019). "In summary, these results indicate that Ori possesses anti-tumor and cisplatin sensitizer potential by the activation of apoptosis, which was mediated by AMPK/Akt/mTOR-dependent autophagy initiation." (PMID 31475112, 2019). "In xenograft tumor tissues, metformin (100 mg/kg) enhanced the suppressive effect of NOMAC (100 mg/kg) on mTOR signaling and increased the average concentration of NOMAC by nearly 1.6 times compared to NOMAC treatment alone." (PMID 31284427, 2019). "It is suggested that in the tumor model (HT1080), 6-shogaol induces premature senescence through increased ROS production, the activation of Akt/mTOR, and the decrease in glucose uptake." (PMID 31505728, 2019). "In order to determine how PYCR1 regulates the physiological processes of tumor cells, we first examined the effect of silencing PYCR1 on the Akt/mTOR pathway." (PMID 31428683, 2019). "Treatment of the PDX from PT14 with both drugs inhibited PI3K/AKT/mTOR and MAPK signaling pathways and decreased PDX tumor volume, suggesting a potential new treatment option for TNBC." (PMID 31018595, 2019). "This is of translational relevance, considering that miR-21 is a well-established oncogenic miR whose major targets include the tumor suppressors PTEN and PDCD4, both of which inhibit PI3K/AKT/mTOR signaling and the Wnt/β-catenin cascade." (PMID 31878245, 2019). "Whereas, overexpressed circ-FBXW7 induced the tumor suppression via reversing the expressions of NEK2, mTOR, and PTEN." (PMID 31519156, 2019). "The primary mechanism of this anti-tumor activity is the simultaneous blockade of EGFR and HER2 activation, which downregulated downstream RAS/RAF/MEK/ERK and PI3K/AKT/mTOR pathways, resulting in G0/G1 arrest in cells." (PMID 30952931, 2019). "It has been reported that C/EBPδ enhanced mTOR stability by directly inhibiting the expression of FBXW7, resulting in elevation of hypoxia and inflammatory signaling which in turn promoted tumor cell survival." (PMID 30791487, 2019). "This experimental design displays the clear mechanism of gigantol treatment in attenuation of the CSC-supportive PI3K/AKT/mTOR and JAK/STAT3 signals at the time of tumor initiation." (PMID 31861050, 2019). "At the end of the 1990s, phosphatase and tensin homolog deleted in chromosome 10 (PTEN) was discovered as a tumor suppressor gene and thereafter it was demonstrated that it acts as a master negative regulator of the PI3K/mTOR/Akt pathway." (PMID 31404976, 2019). "The VEGF signaling pathway acts through the PI3K/mTOR pathway and the PI3K pathway is critical for endothelial cell activation and tumor angiogenesis." (PMID 31273555, 2019). "Co-targeting of mTOR via everolimus along with a PI3K/mTOR dual inhibitor, BEZ235, displayed greater efficacy through activating autophagy, specifically mitophagy, in tumors and led to decreased tumor sizes in a mouse model of HCC." (PMID 30849993, 2019). "New-generation mTOR inhibitors against ATP-binding pocket inhibit both TORC1 and TORC2 and demonstrate more potent anti-tumor effects in vitro and in vivo, however, prospective clinical trials are warranted to prove its efficacy in patients with advanced BTC." (PMID 30682771, 2019). "In tumor cells, HSP90 has an anti-apoptotic effect mediated by mTOR, NF-κB, and FOXO3A; furthermore, it leads to AKT stabilization mitigating apoptosis." (PMID 31354486, 2019). "The combination of eribulin and everolimus, an mTOR inhibitor, resulted in an increased reduction of p-S6K1 and p-S6, a synergistic inhibition of cell survival in vitro, and an enhanced suppression of tumor growth in two orthotopic mouse models." (PMID 31480338, 2019).